INS (insulin)
Diseases named in the same sentence as INS in open-access papers (continued):
Sharing a sentence is not in itself a finding about the gene and the disease.
Insulin resistance (continued). "Aside from that, another factor that contributes to insulin resistance is an accumulation of intramyocellular lipids among the insulin-resistant or T2D populations." (PMID 38137341, 2023). "CO fruit can significantly increase PPARG expression in cells, reversing insulin resistance, enhancing glucose uptake after insulin stimulation." (PMID 37475719, 2023). "Insulin resistance is characterized by a diminished response of peripheral tissues to insulin stimulation, leading to elevated peripheral insulin levels." (PMID 38025699, 2023). "Controlling factors are, on the one side, levels of insulin and insulin resistance, and, on the other side, the quality of cellular resistance to anabolic stress." (PMID 37854186, 2023). "IL-1β decreases IRS-1 tyrosine phosphorylation and its gene expression, inhibiting the insulin signaling pathway required for glycemic control and contributing to the development of insulin resistance." (PMID 37372020, 2023). "For example, the negatively associated protein ARHGDIA is a potent negative regulator of insulin sensitivity, and our fingerprint of insulin resistance contained its homologue ARHGDIB." (PMID 37494090, 2023). "IL-10, which is involved in the regulation of insulin secretion, β-cell apoptosis, and peripheral insulin resistance, was reduced in the T2DM model." (PMID 37229468, 2023). "In summary, the results of our investigation indicate that prolonged consumption of sucralose exacerbates HFD-induced insulin resistance in mice by disrupting insulin signal transduction through the involvement of T1R3 and IRE1α." (PMID 37375718, 2023). "In this study, the inflammatory factors TNF‐α and IL‐1 β decreased significantly, insulin secretion decreased, insulin resistance symptoms alleviated, and the level of HOMA‐β increased in each intervention group." (PMID 37181308, 2023). "Vitamin D3 dose-dependently improves glucose control parameters, as shown by the reduction of fasting blood glucose (FBG), oral glucose tolerance test (OGTT), glycated albumin, insulin levels, and markers of insulin resistance (HOMA-IR)." (PMID 37324274, 2023). "Mining these data reveals that many known regulators of GLUT4 traffic harbour insulin-regulated phosphosites that are dysregulated in insulin resistance." (PMID 37248992, 2023). "The pre-diabetic stage of the disease is mainly characterized by the decreased response of target cells to insulin (insulin resistance), excessive glucose production by the liver, and a low-grade chronic inflammation." (PMID 38104079, 2023). "In women that develop GDM the insulin response becomes inadequate with the advancing pregnancy, as the insulin resistance increases, which leads to hyperglyceamia." (PMID 37079606, 2023). "The pro‐inflammatory cytokines produced by monocytes can induce widespread insulin resistance by inhibiting insulin signaling and impairing lipid metabolism in liver and skeletal muscle tissue." (PMID 38011590, 2023). "LT and AT showed a significant correlation with almost all blood parameters, and the strongest connections were made with T3, T4, BHB and the revised quantitative insulin sensitivity check index of insulin resistance." (PMID 37623900, 2023). "A prospective study of 11 offspring of obese and T2DM patients indicated that weight maintenance with a MUFA-rich diet improved homeostasis model assessment of insulin resistance and fasting pro-insulin levels in insulin-resistant subjects." (PMID 38075228, 2023). "Chronic elevation in insulin signaling molecules is a feature of insulin resistance, thus it is possible that results reflect insulin signaling dysfunction in participants treated with exenatide." (PMID 36258018, 2023). "Intragastric administration of SeNPs decreased hyperglycemia and serum insulin levels and improved insulin resistance of POCS rats, as shown by the reduction in HOMA_IR compared to the untreated PCOS ones." (PMID 36922476, 2023).
Insulin resistance (continued). "Fasting glucose, insulin, insulin resistance expressed in homeostatic model assessment (HOMA-IR) remained unchanged throughout the study, while significant (p < 0.05) decreases in total cholesterol, triglycerides and HDL cholesterol were observed." (PMID 37297894, 2023). "It is also possible that there are several mechanisms leading to insulin progression that are true at the same time or for different clusters of people with insulin resistance." (PMID 38044443, 2023). "Elevated levels of CMPF have the potential to enhance insulin sensitivity, mitigate lipid accumulation, and counteract insulin resistance induced by a high-fat diet." (PMID 38143442, 2023). "A 22‐year‐old woman with T1DM presented with hyperglycaemia and insulin resistance, (1 unit insulin aspart per 4 g carbohydrate and 80 units insulin detemir daily) interspersed with unpredictable hypoglycaemia." (PMID 37562398, 2023). "The release of inflammatory mediators triggered by kidney injury has the potential to disrupt insulin signaling pathways, resulting in the development of insulin resistance." (PMID 37868469, 2023). "Type I levels directly correlate with insulin sensitivity; hence, the reduced expression of type I muscle fibers associated with T2DM is suggested to contribute to skeletal muscle insulin resistance." (PMID 38203642, 2023). "Studies generally focused on the following glycemic indicators: clinical chemistry of glycosylated hemoglobin A1C (HbA1c), fasting plasma glucose (FPG), postprandial glucose (PPG), insulin, and homeostatic model assessment for insulin resistance (HOMA-IR)." (PMID 37960343, 2023). "We first recruited an obese cohort with normal insulin sensitivity (insulin-sensitive obese subjects, hereafter referred to as obese-IS), a MetS cohort with insulin resistance and another 100 matched normal controls with strict criteria." (PMID 37884540, 2023). "Despite resistance to insulin action in adipose tissue, de-novo lipogenesis (DNL), an insulin-dependent process, is stimulated during insulin resistance in the liver." (PMID 37242206, 2023). "Hemin, an activator of HO1, improved glucose tolerance, reduced insulin resistance, and ameliorate the inability of insulin to increase the number of GLUT4 at the cell membrane, the protein required for glucose uptake." (PMID 37298303, 2023). "On the other hand, hepatocytes release miR-3075-enriched EVs during early onset obesity (4 weeks of high-fat diet), which when injected into insulin-resistant recipient mice, attenuate insulin resistance." (PMID 37501663, 2023). "In this study, we also demonstrated significant improvements in postsurgery insulin-responsiveness indices, and a positive correlation between insulin resistance and hepatic VLDL1 production after the surgery." (PMID 37432744, 2023). "Many investigations have shown that defects in the insulin signaling pathway, especially those associated with insulin receptor substrate-2 (IRS-2), are definitely implicated in the pathogenesis of insulin resistance." (PMID 37895151, 2023). "Impaired insulin-stimulated glucose transport (insulin resistance) is thought to be due to reduced GLUT4 delivery to the cell surface, which has been measured in both human muscle and adipose tissue." (PMID 37248992, 2023). "Despite higher insulin and lower lipids in plasma, apoA-IV−/− mice exhibited more insulin resistance than WT mice, and the condition deteriorated over time with the feeding of a high-fat diet." (PMID 38004234, 2023). "In this highly regulated mechanism, insulin resistance occurs when a higher than normal insulin concentration is required to obtain a quantitatively normal response in target tissues, and, among other parameters, HOMA-IR values start to increase." (PMID 38115031, 2023). "It is caused by a combination of genetic, environmental, and lifestyle factors, which lead to problems with insulin production and insulin resistance." (PMID 38283440, 2023).
Insulin resistance (continued). "Insulin resistance (IR) is defined as the subnormal response to insulin action on its target tissues." (PMID 37301876, 2023). "Insulin resistance in the brain is a condition in which the cells become less responsive to the effects of insulin, leading to a decline in cognitive function and an increased risk of neurodegeneration." (PMID 38133370, 2023). "Inflammatory stress is one of the relevant factors contributing to impaired insulin action, insulin resistance, and type 2 diabetes." (PMID 38203600, 2023). "Insulin resistance is manifested as the reduced ability of insulin to inhibit glucose production in the liver and to stimulate the utilization of glucose in adipose tissue and skeletal muscles." (PMID 37998747, 2023). "A different PCOS syndrome explanation theory is based on endocrinological disruptions of the insulin axis, such as hyperinsulinemia and insulin resistance." (PMID 37985173, 2023). "Insulin resistance is the inability of target tissues to respond to insulin due to defects in insulin receptors, thus decreasing insulin-mediated glucose regulation." (PMID 38024366, 2023). "In obese rats, glucose levels were reduced (20%), as well as insulin levels (50%), improving insulin resistance." (PMID 37432178, 2023). "Insulin resistance occurs when body cells, particularly hepatocytes, adipocytes, and muscle cells, become resistant to insulin, resulting in impaired insulin sensitivity." (PMID 37351102, 2023). "In contrast, T2D usually develops later, and the patients are characterized by a blend of two metabolic dysfunctions: insulin resistance and inadequate insulin secretion." (PMID 37762083, 2023). "Despite lower ketogenesis in NAFL subjects with persistent fasting DNL, ketogenesis was disproportionately high relative to insulin (ketone production × [insulin]), consistent with insulin resistance." (PMID 36928190, 2023). "In the liver, IL-6 antagonizes insulin signaling and induces inflammation, which after reaching a certain threshold, leads to insulin resistance and non-alcoholic fatty liver disease." (PMID 37664841, 2023). "In the current study, miR146a-5p represented a positive correlation with insulin resistance and levels of insulin and FBS." (PMID 37917636, 2023). "Genetic studies have described the causal role of insulin in CVD diseases and metabolic studies suggest that prolonged high levels of insulin and concomitant insulin resistance are accelerators of CVD diseases." (PMID 37175639, 2023). "In cases of inadequate insulin action, to compensate for the increased insulin resistance, maternal hyperglycemia, i.e., GDM, ensues." (PMID 36979405, 2023). "GDM shares common pathophysiology with T2DM, involving insulin resistance and impaired insulin secretion." (PMID 38033012, 2023). "When muscle, fat, and liver stop responding properly to insulin, it leads to an impairment of insulin action; this state is known as insulin resistance." (PMID 37298440, 2023). "In the development of the complications, an important role plays insulin resistance related to obesity and participated in the development of T2D, and hyperinsulinemia related to insulin therapy for T1D." (PMID 37065759, 2023). "Arsenic and sucrose induce systemic insulin resistance due to defects in GLUT4 translocation induced by insulin." (PMID 37229459, 2023). "In comparison, strongly statistically significantly higher values in total cholesterol, low-density lipoprotein (LDL), insulin, and homeostatic model assessment of insulin resistance (HOMA-IR) were observed by comparing the same groups." (PMID 37298013, 2023). "Another potential danger of insulin misuse is the development of insulin resistance, a condition where cells become less responsive to the effects of insulin." (PMID 37559855, 2023). "It has also been shown that SHBG levels were inversely proportional to the severity of fatty liver, insulin levels and homeostatic model assessment for insulin resistance (HOMA-IR) values." (PMID 36968815, 2023).
Insulin resistance (continued). "Insulin resistance-adjusted insulin secretion was assessed using Insulin Secretion-Sensitivity Index-2 (ISSI-2), also known as disposition index, expressed as the product of Matsuda index and AUCins/gluc." (PMID 37891561, 2023). "This compound has been shown to have the ability to reduce blood glucose, enhance insulin secretion, improve insulin resistance, and reduce diabetic complications." (PMID 37504903, 2023). "Insulin resistance is a common pathological feature of T2DM wherein insulin-sensitive peripheral tissues, including muscles and adipose tissue, do not respond to insulin stimulation." (PMID 37715850, 2023). "Given that the HOMA-IR formula only includes fasting glucose and insulin, mainly related to insulin resistance in the liver, it seems complicated to obtain a single HOMA-IR cut-off point for all pre-diabetic subjects." (PMID 36788521, 2023). "It is a constant, which means that when an individual’s beta-cells respond to an increase in insulin resistance by increasing insulin secretion appropriately, DI is unchanged, and normal glucose tolerance is retained." (PMID 37781697, 2023). "Insulin resistance in adipose tissue, which in HF is triggered by persistent low-grade inflammation, attenuates the antilipolytic action of insulin and thus also contributes to an increase in serum FFAs and systemic insulin resistance." (PMID 38137418, 2023). "These animals develop brain insulin resistance as indicated by the failure of MBH insulin to suppress WAT lipolysis and hGP despite unaffected insulin signaling in the WAT and the liver." (PMID 37100238, 2023). "In summary, in vivo studies of both murine models and in humans suggest that hepatic insulin signaling is needed for hepatic lipid synthesis, as well as for promoting and progression of fatty liver disease during insulin resistance." (PMID 37367037, 2023). "Elevated endogenous insulin results in weight gain, which in turn aggravates insulin resistance, formulating a pathophysiological vicious cycle." (PMID 36979649, 2023). "We expect that serum fasting insulin concentrations would rise in the setting of metabolic syndrome due to insulin resistance and therefore these insulin concentrations were monitored." (PMID 37335291, 2023). "The discovery of insulin in 1921 introduced a new branch of research into insulin activity and insulin resistance." (PMID 37664840, 2023). "While insulin resistance is the major cause of T2DM, long-standing DM can also impair the insulin-secreting capacity of the pancreas." (PMID 37298274, 2023). "Excessive leptin causes triglyceride accumulation in adipose tissue, the pancreas, and the liver, triggering impaired insulin sensitivity, which leads to insulin resistance." (PMID 37174950, 2023). "The association of top metabolites differencing IS and IR in IRA with insulin and C-peptide is expected, as they are markers of insulin resistance." (PMID 37175541, 2023). "Insulin resistance is defined as a decreased sensitivity or reactivity to insulin's metabolic actions, including insulin-mediated glucose handling." (PMID 37370012, 2023). "The bigger the OS that can cause damage to cellular macromolecules becomes, the greater the intensity of inflammatory reactions and mitochondrial dysfunction, ultimately leading to less insulin secretion and more insulin resistance." (PMID 37664859, 2023). "This, in turn, triggers inflammation in organs targeted by insulin and initiates insulin resistance." (PMID 37564976, 2023). "First, BBR dramatically reduces serum insulin levels and alleviates insulin resistance, working through promoting RXRA, reducing KCNQ1 and NR3C1, and attenuating palmitate-induced mitochondrial injury and apoptotic death." (PMID 37009462, 2023). "In vitro studies using 3T3-L1 adipocyte cell line showed that resistin neutralization by resistin antiserum enhanced insulin-stimulated glucose uptake and decreased insulin resistance." (PMID 38136564, 2023).
Insulin resistance (continued). "The plasma insulin level was measured by ELISA to confirm insulin resistance (P = 0.87, 0.898, 0.98, 0.981 and 0.999 between the two groups at time points 0, 30, 60, 90 and 120 min, respectively; two‐way ANOVA)." (PMID 37139700, 2023). "Conversely, peripheral insulin resistance induced by high sugar leads to accumulation of insulin, which results in hyperinsulinemia." (PMID 37867511, 2023). "Previous studies have found that PAK2 is involved in neuronal insulin signaling, glucose uptake and insulin resistance." (PMID 37610708, 2023). "Skeletal muscle insulin resistance occurs when the normal amount of insulin is inadequate for promoting the expected uptake of glucose." (PMID 37371869, 2023). "It is the primary site of lipid utilization, and it stands for the majority of whole-body insulin-mediated glucose uptake, both features closely connecting SkM to obesity and insulin resistance." (PMID 37569453, 2023). "As a result, the body endeavors to counteract heightened insulin resistance by augmenting insulin secretion, which is proved by elevated insulin levels (hyperinsulinemia) observed in individuals with periodontitis." (PMID 38132215, 2023). "Overactivation of MR suppresses the phosphorylation of PI3K/AKT and leads to insulin resistance, whereas blockade of MR enhances insulin sensitivity in obese mice, suggesting that MR is critical in the pathogenesis of insulin resistance." (PMID 37734559, 2023). "Treatment of insulin-resistant HepG2 cells with PSC-FEs caused an obvious increase in glucose consumption, indicating PSC-FEs can mitigate the induced insulin resistance in HepG2 cells." (PMID 37158952, 2023). "Type 2 diabetes, on the other hand, mainly arises from a combination of insulin resistance and decreased insulin production." (PMID 38283440, 2023). "The potential of food to trigger the release of insulin after a meal is crucial when considering the prevention and control of insulin resistance and T2DM." (PMID 38049837, 2023). "To evaluate the candesartan-mediated therapeutic potential of enhanced insulin signaling in vivo, we examined the effects of candesartan administration on insulin resistance and metabolic profiles in HFD-fed mice." (PMID 37121975, 2023). "It has been postulated that insulin resistance induced by free fatty acids is a consequence of alterations in the transduction of the postreceptor insulin signal inside the cell." (PMID 37241071, 2023). "Two primary components in the pathogenesis of T2DM are insulin resistance and impaired insulin secretion." (PMID 37313245, 2023). "Several epidemiological studies and experimental models of insulin resistance and hyperinsulinemia have shown a correlation between insulin levels and cancer development." (PMID 36975518, 2023). "The diabetogenic effect of COVID-19 has been related to inflammation and oxidative stress, which can lead to pleiotropic alterations in glucose metabolism, including impaired insulin activity and insulin resistance." (PMID 37684387, 2023). "Further, RTV, NFV, and SQV not only induce peripheral insulin resistance but also impair glucose-stimulated insulin secretion from beta cells." (PMID 37175645, 2023). "Increased glucose metabolism was influenced 45% by extracellular glucose concentration and 55% by insulin, the latter decreasing in an experimental model of insulin resistance." (PMID 38292764, 2023). "What’s worse, the activation of sympathetic nervous system evokes insulin resistance through mobilizing free fatty acids (FFAs) from adipose tissue and stimulating serine/threonine kinases that interfere with the insulin signaling." (PMID 37403082, 2023). "Analysis of fasting blood glucose and insulin levels together, in the homeostatic model assessment for insulin resistance (HOMA-IR), showed that HAMSB-fed mice had a significantly lower HOMA-IR compared to Ctr mice." (PMID 36901964, 2023).